SOCS6 (suppressor of cytokine signaling 6)
Description:
SOCS family proteins form part of a classical negative feedback system that regulates cytokine signal transduction. May be a substrate recognition component of a SCF-like ECS (Elongin BC-CUL2/5-SOCS-box protein) E3 ubiquitin-protein ligase complex which mediates the ubiquitination and subsequent proteasomal degradation of target proteins (By similarity). Regulates KIT degradation by ubiquitination of the tyrosine-phosphorylated receptor.
Synonyms: SOCS-6; CIS-4; SOCS-4; CIS4; SOCS4; SSI4; HSPC060; STATI4; STAI4; Cish4
Tractability: Small molecule: it has a binding pocket of medium quality. PROTAC: ubiquitination databases record sites on it.
Gene: Protein-coding gene on chromosome 18 (70,288,888 to 70,330,199, forward strand). Ensembl gene ENSG00000170677.
Subcellular location (Human Protein Atlas): Nuclear speckles; Cytosol
Pathways (Reactome):
Immune System: Negative regulation of FLT3
Metabolism of proteins: Neddylation
Signal Transduction: Regulation of KIT signaling
Gene Ontology:
Molecular function: protein binding; signaling adaptor activity
Biological process: proteasomal protein catabolic process; cell surface receptor signaling pathway via JAK-STAT; defense response; intracellular signal transduction; protein ubiquitination; regulation of growth
Cellular component: immunological synapse; cytoplasm; cytosol
Genetic constraint (gnomAD): Loss-of-function variants: 5 observed, 32.99 expected, observed/expected ratio (o/e) 0.15, 90% interval 0.078 to 0.32. The upper end of that interval is the gene's LOEUF score, 0.32, which puts it in group 1 of 6, group 1 being the genes least tolerant of losing a copy. Missense variants: 570 observed, 689.83 expected, observed/expected ratio (o/e) 0.83, 90% interval 0.77 to 0.89. Synonymous variants: 264 observed, 263.53 expected, observed/expected ratio (o/e) 1, 90% interval 0.9 to 1.11.
Homologues: Orthologues: chimpanzee SOCS6 (99% identical), macaque SOCS6 (99% identical), guinea pig SOCS6 (95% identical), dog SOCS6 (94% identical), pig SOCS6 (92% identical), rabbit SOCS6 (87% identical), mouse Socs6 (85% identical), rat Socs6 (84% identical), tropical clawed frog socs6 (83% identical), zebrafish socs6b (70% identical), zebrafish socs6a (70% identical), Drosophila melanogaster Socs36E (16% identical), and 1 more. Paralogues in human: SOCS7 (26% identical), SOCS5 (20% identical), SOCS4 (17% identical), CISH (13% identical), SOCS2 (12% identical), SOCS3 (11% identical), SOCS1 (10% identical).
Diseases named in the same sentence as SOCS6 in open-access papers:
SOCS6 is named in the same sentence as 57 diseases in open-access papers, as found by Europe PMC text mining. Sharing a sentence is not in itself a finding about the gene and the disease. The quoted sentences say what the papers report.
pancreatic cancer (9 papers, 2016 to 2024). "MiR-424-5p is significantly upregulated in pancreatic cancer and regulates the ERK1/2 signaling pathway through the negative regulation of SOCS6, which leads to the proliferation, migration and invasion of pancreatic cancer cells." (PMID 35409396, 2022). "Previous studies have shown that miRNA-424-5p suppresses the expression of SOCS6 in pancreatic cancer and inhibits the Akt3/E2F3 axis and tumour growth in hepatocellular carcinoma." (PMID 29716627, 2018). "Suppressor of cytokine signaling 6 (SOCS6) is widely expressed in numerous tissues and is down-regulated in many cancers, including lung, colorectal, gastric, ovarian, stomach, thyroid, hepatocellular, and pancreatic cancer." (PMID 27811366, 2016).
gastric cancer (8 papers, 2012 to 2022). A primary or metastatic malignant neoplasm involving the stomach. "In gastric cancer, SOCS6 loss in conjunction with promoter hypermethylation results in transcriptional silencing." (PMID 22363434, 2012). "Recent evidence in gastric cancer suggests that SOCS6 maybe the candidate gene for the 18q22 copy number alteration and the loss of SOCS6 appears to be a critical genetic alteration in the development of certain subtypes of gastric cancer." (PMID 22363434, 2012). "The tumor suppression of SOCS6 was discovered in lung cancer, cervical cancer, gastric cancer and other types of cancers." (PMID 33712005, 2021). "SOCS6 is known to suppress tumor growth in multiple cancers such as gastric cancer, prostate cancer, non-small cell lung cancer and cervical cancer, through regulating tumor angiogenesis and cell apoptosis." (PMID 33712005, 2021). "In gastric cancer, miR-17-5p was significantly upregulated in GC tissues and increased GC growth by repressing SOCS6 or modulating p21 and TP53INP129,30." (PMID 30683847, 2019). "High miR-17-5p expression inhibits suppressor of cytokine signaling 6 (SOCS6), which promotes the proliferation of gastric cancer cells." (PMID 27464701, 2016). "Besides its roles in lung squamous carcinoma, prostate cancer and hepatocellular carcinoma, SOCS6 could also inhibit the growth of gastric cancer, non-small cell lung cancer and cervical cancer via inhibiting angiogenesis, suppressing tumor cell proliferation and promoting apoptosis." (PMID 34895274, 2021).
hepatocellular carcinoma (8 papers, 2014 to 2026). A malignant tumor that arises from hepatocytes. "Recent reports have suggested that low SOCS6 levels are associated with poor prognosis in hepatocellular carcinoma and prostate cancer." (PMID 25180228, 2014). "Similarly, SOCS6 was down-regulated in hepatocellular carcinoma and low expression of SOCS6 was significantly associated with progression, high recurrence risk and worse recurrence-free survival of hepatocellular carcinoma." (PMID 34895274, 2021). "In hepatocellular carcinoma, PETEN, a tumour suppressor gene connected to SOCS6, showed a compensating situation-dependent impact." (PMID 41514679, 2026). "Furthermore, a high rate of methylation was detected on several SOCS genes, such as SOCS1 in hepatocellular carcinoma, SOCS3 in head and neck squamous cell carcinoma, and SOCS6 in GC." (PMID 33937336, 2021). "It was reported that SOCS6 could decrease the protein levels of p-STAT3 and HIF-1α in breast cancer and hepatocellular cancer." (PMID 32519748, 2020).
prostate carcinoma (6 papers, 2014 to 2022). A carcinoma that arises from epithelial cells of the prostate gland. "Suppression of SOCS-6 (an inhibitor of cytokine-6 signaling) correlated with malignant progression of human prostate cancer, and it was associated with late clinical stage (p = 0.029) and metastasis in the LN (p = 0.013)." (PMID 35330327, 2022). "SOCS6 overexpression inhibited the invasion, the migration of prostate cancer cells, the growth of tumor xenotransplants, and angiogenesis." (PMID 35330327, 2022). "Angiogenesis of prostate cancer was inhibited possibly via suppressor of cytokine signaling 6 (SOCS6) overexpression-mediated F7 downregulation." (PMID 34066023, 2021).
non-small cell lung carcinoma (5 papers, 2016 to 2022). A group of at least three distinct histological types of lung cancer, including non-small cell squamous cell carcinoma, adenocarcinoma, and large cell carcinoma. "It has been reported that hsa_circ_0015278 regulates the progression of non-small cell lung cancer through the miR-1278/SOCS6 signaling axis." (PMID 36612069, 2022). "For example, hsa-miR-1260b is upregulated in non-small cell lung cancer (NSCLC) and promotes tumor growth, invasion, and metastasis by targeting PTPRK (Protein Tyrosine Phosphatase Receptor Type K) and SOCS6 (Suppressor of Cytokine Signaling 6)." (PMID 34150610, 2021). "miR-1260b was suggested to directly suppress suppressor of cytokine singling 6 (SOCS6) expression and activate KIT proto-oncogene (KIT) signaling in non-small-cell lung cancer (NSCLC)." (PMID 32252322, 2020).
colorectal cancer (4 papers, 2014 to 2022). A primary or metastatic malignant neoplasm that affects the colon or rectum. "Other examples include SOCS6, as its loss was reported in more than 50% of patients with gastric or colorectal cancer, with SOCS6 inactivation predominantly caused by allelic loss or promoter hypermethylation." (PMID 24757565, 2014). "A study into the colorectal cancer promoting mechanism of miR-301a, which is upregulated in colorectal cancers, revealed that miR-301a expression confers growth and invasion by downregulating SOCS6 expression." (PMID 29579063, 2018). "SOCS6 mRNA was significantly reduced in tumors versus normal tissue in the TCGA colorectal carcinoma dataset." (PMID 25180228, 2014). "The SOCS6 gene is located in an interval frequently deleted in colorectal cancer." (PMID 25180228, 2014). "SOCS6 mRNA was significantly reduced in a second dataset, which contains 65 rectal adenocarcinomas and 65 controls from adjacent normal tissue (Fig5A), as well as other colorectal cancer datasets." (PMID 25180228, 2014). "Depletion of SOCS6 increased the ability of DLD1 and HCT116 colorectal cancer cells to form colonies in soft agar, but had limited impact on colony formation by SW48 cells (Fig5F)." (PMID 25180228, 2014).
Insulin resistance (4 papers, 2011 to 2021). Increased resistance towards insulin, that is, diminished effectiveness of insulin in reducing blood glucose levels. "SOCS6 associates with and inhibits the insulin receptor and is related to cytokine-mediated insulin resistance in SOCS6-overexpressing transgenic mice, while human SOCS7 interacts with STAT5 or STAT3, to prevent nuclear translocation and to attenuate prolactin, growth hormone, and leptin signaling." (PMID 30884777, 2019). "SOCS6 was first described to inhibit insulin receptor, which mediates cytokine-induced insulin resistance." (PMID 33712005, 2021). "The SOCS protein family could contribute to insulin resistance, suppressor of cytokine signaling 6(SOCS6) was up-regulated and involved in the intracellular signal transduction pathway with Glucokinase (GCK)." (PMID 31805951, 2019). "The SOCS6 protein, a less extensively studied SOCS family member, has been shown to induce insulin resistance in the retina and promote survival of the retinal neurons." (PMID 22125600, 2011).
periodontitis (4 papers, 2021 to 2022). An acute or chronic inflammatory process that affects the tissues that surround and support the teeth. "It is demonstrated that NIFK-AS1 increases the expression of Notch1 by interacting with miR-146a in endometrial cancer, and FGD5-AS1 affects periodontitis by regulating the FGD5-AS1/miR-142-3p/SOCS6 axis." (PMID 33936172, 2021). "FGD5-AS1 was first identified as being involved in the lncRNA-associated ceRNA network of periodontitis, and the upregulation of FGD5-AS1 could protect against periodontitis via regulating the miR-142-3p/SOCS6/NF-κB signals." (PMID 34046402, 2021).
breast carcinoma (3 papers, 2020 to 2021). "As a tumor suppressor, SOCS6 was shown to inhibit cell proliferation in breast cancer and was usually suppressed in tumor cells such as gastric, liver and prostate tumor cells." (PMID 34120621, 2021). "Furthermore, miR-155 can reverse tamoxifen resistance by activating the suppressor of cytokine signaling 6 (SOCS6), a signal transducer and activator of the transcription 3 pathway in breast cancer." (PMID 34210046, 2021). "Therefore, further studies are still required to confirm the role of SOCS6 in breast cancer." (PMID 34120621, 2021).
cervical cancer (3 papers, 2015 to 2021). A primary or metastatic malignant neoplasm involving the cervix. "Clearly, SOCS6 is actively involved in HPV E6 stabilizing YAP protein in the cervical cancer cells." (PMID 26417066, 2015). "However, expression of HPV16 E6 in HT3 cells reduced SOCS6 protein levels, but increased YAP protein levels, suggesting that SOCS6 may be involved in HPV E6-mediated YAP protein stabilization in cervical cancer cells." (PMID 26417066, 2015).
co-infection (2 papers, 2016 to 2022). "The expression of chemokine (C-X-C motif) ligand 10 (CXCL10) was shown to be indirectly modulated by miR-200a-3p by targeting suppressor of cytokine signaling-6 (SOCS-6) to regulate the immune response to co-infection." (PMID 35986232, 2022). "In addition, the expression levels of SOCS-6, which is a regulator of the JAK-STAT pathway and of CXCL10, which is an interferon-γ-induced protein, were associated with viral and bacterial co-infection and pneumonia severity." (PMID 35986232, 2022). "Our study suggests co-infection leads to overexpression of miR-200a-3p, which in turn targets and downregulates the JAK-STAT regulator SOCS-6 and consequently increases CXCL10 (IP-10) expression." (PMID 27922126, 2016). "We demonstrated that endogenous miRNA-200a-3p, whose expression was synergistically induced following co-infection, indirectly regulates CXCL10 expression by targeting suppressor of cytokine signaling-6 (SOCS-6), a well-known regulator of the JAK-STAT signaling pathway." (PMID 27922126, 2016).
glioblastoma (2 papers, 2021 to 2022). The most malignant astrocytic tumor (WHO grade IV). "Interfering with NTSR1 expression causes anti-invasive effects through the Jun/miR-494/SOCS6 axis in glioblastoma cells." (PMID 36439693, 2022). "Interfering with NTSR1 expression exhibits anti-invasive effects through the Jun/miR-494/SOCS6 axis in glioblastoma cells." (PMID 36439693, 2022). "In glioblastoma, up-regulation of miR-494 could result in reduced expression of SOCS6." (PMID 34895274, 2021).
liver cancer (2 papers, 2023 to 2024). An epithelial or non-epithelial malignant neoplasm that arises from the liver. "SOCS1 alterations through SOCS7 and CISH alterations were detected in liver cancer tissues at the following frequencies: SOCS1, 1.1%; SOCS2, 0.8%; SOCS3, 6%; SOCS4, 0.3%; SOCS5, 1.3%; SOCS6, 1.3%; SOCS7, 2.4%; and CISH, 2.7%." (PMID 39307915, 2024). "The miRNA-21 was demonstrated to promote the proliferation, migration, and invasion of liver cancer cells through inhibiting FASLG, SOCS6, and KLF5." (PMID 37704828, 2023).
oral squamous cell carcinoma (2 papers, 2022 to 2023). "In oral squamous cell carcinoma (OSCC) and CML, MEG3 promoted apoptosis by sponging miR-548d-3p and miR-147, thereby promoting suppressor of cytokine signaling 5 (SOCS5) and suppressor of cytokine signaling 6 (SOCS6) expression while inhibiting the JAK-STAT signaling pathway." (PMID 36551518, 2022).
ovarian carcinoma (2 papers, 2025). A malignant neoplasm originating from the surface ovarian epithelium. "Another study reported that CAFs secrete sEVs carrying miR-296-3p, which exacerbates ovarian cancer progression by targeting PTEN and SOCS6, and stimulating the Akt/STAT3 pathway." (PMID 40008006, 2025). "Interestingly, miR-296-3p encapsulated by sEVs from CAFs has been shown to regulate intercellular communication and promote ovarian cancer development by affecting the PTEN/Akt and SOCS6/STAT3 signaling pathways." (PMID 40008006, 2025). "Additionally, it controls epithelial-mesenchymal transition to suppress proliferation and metastasis in ovarian cancer and hampers malignant transformation in NSCLC via the miR-141-3p/LatS2 axis and the miR-1278/SOCS6 axis." (PMID 39866239, 2025).
renal fibrosis (2 papers, 2020 to 2022). A final common manifestation of a wide variety of chronic kidney diseases characterized by glomerulosclerosis and tubulointerstitial fibrosis. "hsa-mir-155-5p can also regulate the pathogenesis of renal fibrosis via targeting SOCS1 and SOCS6." (PMID 35755170, 2022).
atherosclerosis (1 paper, 2025). A disease characterized by the build-up of fatty material and calcium deposition in the arterial wall resulting in partial or complete occlusion of the arterial lumen. "Subsequent functional annotation identified eight atherosclerosis-relevant candidate genes: transcription factors (KLF12, KLF6, KLF9, and MEF2C), epigenetic regulators (HDAC9), and signaling molecules (YAP1, SOCS6, and CDC25A)." (PMID 41373654, 2025).
bladder cancer (1 paper, 2021). "While in bladder cancer cells, lncRNA NBAT1 could regulate SOCS6 expression via miR-21-5p." (PMID 34895274, 2021).
cerebral infarction (1 paper, 2020). An ischemic condition of the brain, producing a persistent focal neurological deficit in the area of distribution of the cerebral arteries. "In this study, we transplanted SOCS6-peptide-delivered epidermal stem cells into the brain of cerebral infarction model rats and observed that the grafted cells differentiated into GABAnergic neurons in the rodent brain." (PMID 32668737, 2020).
colon carcinoma (1 paper, 2022). "The current study aimed to investigate the effect of valproic acid (VPA) on SOCS-1, SOCS-2, SOCS-3, SOCS-5, SOCS6, and SOCS-7 gene expression and cell growth inhibition in colon carcinoma IS1, IS2, and IS3 cell lines." (PMID 35611249, 2022). "The results of the current study demonstrate that VPA plays its role through the upregulation of SOCS-1, SOCS-2, SOCS-3, SOCS-5, SOCS6, and SOCS-7 genes, resulting in cell growth inhibition and apoptosis induction in colon carcinoma IS1, IS2, and IS3 cell lines." (PMID 35611249, 2022).
COVID-19 (1 paper, 2023). A disease caused by infection with severe acute respiratory syndrome coronavirus 2. "In the same line, miR-200a-3p overexpression downregulates SOCS-6, also a JAK–STAT regulator, and in COVID-19 patients this miRNA is in fact overexpressed; moreover, miR-200c-3p is positively correlated with IL-6 levels and in one study included in the review this miRNA was overexpressed." (PMID 36834984, 2023).
diabetic retinopathy (1 paper, 2023). "Overexpression of miR-380-3p activated inflammation, oxidative stress, and apoptosis by targeting suppressor of cytokine signaling 6 in retinal epithelial cells with diabetic retinopathy." (PMID 37170511, 2023).
glioma (1 paper, 2024). A benign or malignant brain and spinal cord tumor that arises from glial cells (astrocytes, oligodendrocytes, ependymal cells). "When interfering with neurotensin 1 receptor expression, an anti-invasion effect occurs through the Jun/miR-494/SOCS6 axis in glioma cells." (PMID 39063232, 2024).
Kaposi's sarcoma (1 paper, 2021). A malignant neoplasm characterized by a vascular proliferation which usually contains blunt endothelial cells. "A more recent study reported that miR-k12-1-5p could lead to decreased expression of SOCS6 in Kaposi’s sarcoma." (PMID 34895274, 2021).
medulloblastoma (1 paper, 2021). A malignant, invasive embryonal neoplasm arising from the cerebellum. "Probe cg11890453, located in the 5′UTR region of SOCS6, is hypomethylated in medulloblastoma." (PMID 36303797, 2021).
Obesity (1 paper, 2018). Accumulation of substantial excess body fat. "The SOCS6 gene has not yet been associated with a disease, however it may be related to syndromic obesity." (PMID 30258496, 2018).
osteosarcoma (1 paper, 2022). A usually aggressive malignant bone-forming mesenchymal neoplasm, predominantly affecting adolescents and young adults. "miR-19 has also been found to promote the progression of osteosarcoma by targeting and downregulating Socs6 in association with Janus kinase 2 (JAK2)/signal transducer and activator of transcription 3 (STAT3) signaling." (PMID 35126805, 2022).
psoriasis (1 paper, 2022). An autoimmune condition characterized by red, well-delineated plaques with silvery scales that are usually on the extensor surfaces and scalp. "This work evaluated the expression levels of the circulating miR-203 target genes SOCS3, SOCS6, TP63, TNF-, IL8, and IL24 in psoriasis patients." (PMID 36341243, 2022). "In order to gain a better knowledge of miRNAs role in the disease, the current study looked into the influence of miR-203 expression and its target genes SOCS3, SOCS6, TP63, TNF-α, IL-8, and IL-24 on the pathogenesis and clinical course of psoriasis." (PMID 36341243, 2022). "We conducted this study to evaluate miR-203 expression level in the plasma of psoriasis patients to investigate its role and target genes SOCS3, SOCS6, P63, TNF-α, IL-8, and IL-24 in the systemic pathogenesis of this disease and correlate these data with the disease course." (PMID 36341243, 2022).